CDKN1B (cyclin dependent kinase inhibitor 1B)
Diseases named in the same sentence as CDKN1B in open-access papers (continued):
Sharing a sentence is not in itself a finding about the gene and the disease.
pituitary adenomas (29 papers, 2012 to 2026). "On the other hand, mutations in CDKN1B are very rare in cases of isolated pituitary adenomas, sporadic gigantism or acromegaly among the pediatric population." (PMID 39336996, 2024). "The last MEN syndrome discovered is MEN4, where PVs in the tumor suppressor gene CDKN1B increase the susceptibility of developing primary hyperparathyroidism and pituitary adenomas." (PMID 35954404, 2022). "A heterozygous germline nonsense mutation in the CDKN1B gene was identified in a patient with a GH-secreting pituitary adenoma, parathyroid adenoma, and segregation within the family." (PMID 35323929, 2022). "Genetic analysis revealed the mutation p.I119T (c.356T>C) of exon 1 of CDKN1B, a mutation already reported in the literature in association with early-onset pituitary adenomas." (PMID 35355569, 2022). "Cyclin-dependent kinase inhibitor 1B (CDKN1B), also known as p27Kip1, is a crucial cell cycle regulatory protein that plays a significant role in cell cycle control; the mutations in the CDKN1B/p27Kip1 gene are reported to be associated with pituitary adenomas." (PMID 39765842, 2024). "In addition, a mouse with a mutation (Ser10Ala) of Cdkn1b, which encodes p27, a member of the p21 family of CKIs that abrogated its ability to bind CDKs, resulted in the development of pituitary adenomas." (PMID 26320859, 2016). "Cases associated with CDKN1B mutations display a heterogeneous phenotype, referred to as MEN4, encompassing parathyroid and pituitary adenomas, neuroendocrine tumors and various benign and malignant tumors." (PMID 28533356, 2017). "Germline CDKN1B pathogenic variants result in multiple endocrine neoplasia type 4 (MEN4), an autosomal dominant hereditary tumor syndrome variably associated with primary hyperparathyroidism, pituitary adenoma, and duodenopancreatic neuroendocrine tumors." (PMID 35323929, 2022). "TRβPV/PV mice possess a knock-in mutation of the TRβ gene and spontaneously develop TSH-secreting pituitary adenomas (TSHoma) with age; MENX rats harbor biallelic frameshift mutations of the CDKN1B gene (encoding p27KIP1) and develop pituitary adenomas alongside multiple other endocrine tumors." (PMID 26793165, 2015). "In addition, three germline CDKN1B variants were detected in three paediatric patients with pituitary adenomas, with no other manifestations related to MEN4." (PMID 36334246, 2023). "Assessing systemic hormone levels and fat pad transplantation studies demonstrated that the observed alterations are not due to the intrinsic properties of Cdkn1b-/- mammary epithelial cells, but caused by the perturbed endocrine environment possibly triggered by pituitary adenomas and hyperplasia." (PMID 30893315, 2019). "Whereas 20% of the pituitary adenomas in patients with MEN1 are classified as prolactinomas, this type of tumor has not been reported in patients with MEN4, possibly indicating differential effects of CDKN1B and MEN1 mutations on development of lactotropic tumors in the pituitary gland." (PMID 30990521, 2019). "Known pheo/PGL genes (SDHA-D, SDHAF2, RET, VHL, TMEM127, MAX, FH) and pituitary adenoma genes (MEN1, AIP, CDKN1B) were sequenced using next generation or Sanger sequencing." (PMID 25494863, 2015). "CDK inhibitors CDKN1B (p27), CDKN2A (p16), and CDKN2C (p18) are involved in G1-S transition, provide growth inhibitory signals and exhibit alterations in pituitary adenomas." (PMID 23226476, 2012). "Contrary to the pituitary gland adenomas, we did not observe any neoplastic changes in the mammary epithelium of Cdkn1b-/- rats nor any signs of nuclear abnormalities described in fibroblast cultures derived from Cdkn1b-/- mice." (PMID 30893315, 2019).
colorectal cancer (27 papers, 2008 to 2025). A primary or metastatic malignant neoplasm that affects the colon or rectum. "In addition, four other variants of CDKN1B have been reported in patients with medulloblastoma, paraganglioma, acute lymphoblastic leukaemia and familial colorectal cancer." (PMID 36334246, 2023).
pituitary tumor (25 papers, 2003 to 2025). A benign or malignant neoplasm affecting the pituitary gland. "To date, less than 50 cases with CDKN1B mutations (the majority of patients presenting with hyperparathyroidism) have been noted, one-third of those conjoined with pituitary tumours." (PMID 33805450, 2021). "This is an important observation as Rb1+/-; Cdkn1a-/- mice are susceptible to pituitary tumors and have similar survival as for Rb1G/+; Cdkn1b-/- animals, this indicates that the Rb1G mutation cooperates preferentially with p27 loss." (PMID 30703085, 2019). "To date, homologous deletions of 10 different genes, which are Men1, Cdkn1b, Prkar1a, Rb, Cdkn2b (encoding p19), Drd2, Cdkn2c (encoding p18), Aip, Prl and Prlr, have been reported to yield mouse knockout models for pituitary tumours." (PMID 26320859, 2016). "MEN1 and CDKN1B testing is recommended in patients with personal or family history of kidney stones, neuroendocrine tumours or pituitary tumours." (PMID 33805450, 2021). "Because Rb1G/G; Cdkn1b-/- mice develop pituitary tumors with complete penetrance, we also inspected whole mount views of pituitary glands to search for even subtle signs of overgrowth in Rb1G/G; Cdkn1a-/- mice at survival endpoints." (PMID 30703085, 2019). "The importance of p27KIPl in regulating the cell cycle was further confirmed by the fact that mice that were null for CDKN1B grew faster, exhibited organomegaly, and had a higher incidence of pituitary tumors in comparison to age-matched controls." (PMID 30700046, 2019). "The phenotype of Cdkn1b-/- rats showed similarities to that of Cdkn1b-/- mice including increased body and organ size with normal morphology and pituitary tumors." (PMID 30893315, 2019). "Conventional knockout mice have been generated to assess the direct effect of several genes linked to familial pituitary tumors such as MEN1, CDKN1B, and AIP in pituitary-tumor development." (PMID 25136513, 2014). "Currently, it is not possible to determine whether this difference is due to a statistical issue related to the small number of cases or to a specific effect of CDKN1B on pituitary tumor development." (PMID 35355569, 2022). "Thirty cases representing 16 different CDKN1B variants have previously been reported, and these cases presented primarily with primary hyperparathyroidism and functioning and nonfunctioning pituitary tumors." (PMID 30990521, 2019). "In conjunction with prior results that Rb1G/G; Cdkn1b-/- animals succumb to pituitary tumors, and that Rb1+/-; Cdkn1a-/- mice have accelerated pituitary tumorigenesis, these genetic crosses provide two simple conclusions relating to RB function in cell cycle and cancer susceptibility." (PMID 30703085, 2019). "Recently, other germline mutations involving four cyclin-dependent kinase inhibitor genes (CDKN1A/p15, CDKN2C/p18, CDKN2B/p21 and CDKN1B/p27) and, in patients with pituitary tumors, the AIP gene have been found in a minority of patients with clear MEN1 phenotype." (PMID 23259638, 2012). "Besides the proband (IV:4), nonfunctioning pituitary tumors were identified in three carriers of the CDKN1B variant, including two microadenomas (III:4 and III:7) and one macroadenoma (IV:1), with functionality classified on the basis of measurements of IGF-1 and prolactin." (PMID 30990521, 2019).
cervical carcinoma (20 papers, 2002 to 2025). A carcinoma arising from either the exocervical squamous epithelium or the endocervical glandular epithelium. "Here we shed light on the previously unrecognized molecular mechanism underlying aberrant down-regulation of CDKN1B in cervical carcinoma and uncovered the MIAT-miR-150-5p-CDKN1B signaling pathway in this disease." (PMID 32549789, 2020). "In addition, CDK inhibitors are transcriptional targets of EMT-TFs; SNAIL activated p21CIP1-encoding gene CDKN1A; and SLUG induced both CDKN1A and CDKN1B (codes for p27KIP1) in cervical carcinoma cells." (PMID 37259089, 2023). "Our study for the first time highlighted the critical role of MIAT-miR-150-5p-CDKN1B axis in cervical carcinoma." (PMID 32549789, 2020). "Mechanistically, MIAT regulated CDKN1B expression via competition with miR-150, and miR-150-inhibition directly suppressed cervical cancer cell growth." (PMID 32549789, 2020). "Next, we sought to validate the pathologic role of MIAT-miR-150-5p-CDKN1B in cervical cancer via direct inhibition of miR-150-5p." (PMID 32549789, 2020). "Our study characterized the anti-tumor property of MIAT in cervical cancer and elucidated its competitively regulation of CDKN1B with miR-150." (PMID 32549789, 2020). "Loss of RB1 function, which is a well known phenomenon in cervical cancer leads to expression of Cyclin D1, over-expression/amplification of CDK4, and/or loss of the CDKN1B, CDKN2A and CDKN2B." (PMID 26701206, 2016). "In summary, here we identified the anti-tumor property of MIAT through endogenously competing for miR-150 in regulation of CDKN1B, which consequently contributed to our comprehensive understanding of mechanistic involvements of long non-coding RNA in cervical carcinoma." (PMID 32549789, 2020).
glioblastoma (19 papers, 2012 to 2025). The most malignant astrocytic tumor (WHO grade IV). "By catalyzing H3K27me3, EZH2 represses a series of tumor suppressor genes associated with the tumorigenic properties of glioblastoma, including CDKN1B, RUNX3, and HOXA5." (PMID 35927718, 2022). "CDKN1B mRNA is a target for miR-221- and miR-222-mediated repression, and high levels of these two miRNAs correlate inversely with low CDKN1B levels in cancer, for example in glioblastoma." (PMID 33401540, 2021). "In glioblastoma cells, high PTK2 expression can increase the expression of CCND1 and CCNE, reduce the expression of CDKN1B (p27Kip1) and p21Waf1, and enhance the activity of CDK4, thereby promoting the G1/S phase transformation of glioblastoma cells." (PMID 36770809, 2023).
multiple endocrine neoplasia (19 papers, 2010 to 2025). Multiple endocrine neoplasia (MEN) is a group of rare inherited cancer syndromes characterized by the development of two or more endocrine gland tumors, sometimes with tumor development in other tissues or organs. "Germline mutations of CDKN1B have also been identified as the cause of a type of multiple endocrine neoplasia, a rare autosomal dominant disease characterized by multiple endocrine cancers." (PMID 39936980, 2025). "Protein kinase mutations induce Carney Complex, whereas mutations in menin (MEN1) or cyclin-dependent kinase inhibitor 1B (p27, MEN4) cause multiple endocrine neoplasia, a genetic illness." (PMID 39812047, 2025). "MEN4 is the most recent member of the MEN syndromes group; it was first described in 2006 as an autosomal dominant disorder due to a mutation in the cyclin-dependent kinase inhibitor 1B (CDNK1B) gene." (PMID 39336996, 2024). "In rats, a germline Cdkn1b homozygous inactivation has been identified as causative of a form of multiple endocrine neoplasia, called multiple endocrine neoplasia X (MENX)." (PMID 33316141, 2021). "Germline mutations in the CDKN1B gene have been recently associated with the development of a multiple endocrine neoplasia syndrome both in humans (MEN4, MIM 610755) and in rats (MENX)." (PMID 23555276, 2013). "Germline mutations in the cyclin-dependent kinase inhibitor, CDKN1B, have been described in patients with multiple endocrine neoplasia (MEN), a cancer predisposition syndrome with adult onset neoplasia and no additional phenotypes." (PMID 23505216, 2013). "The finding that a spontaneous germline frameshift mutation in Cdkn1b (encoding p27) causes the MENX multiple endocrine neoplasia syndrome in the rat provided the first evidence that Cdkn1b is a tumor susceptibility gene for endocrine tumors." (PMID 20492666, 2010). "We recently identified a Cdkn1b germline frameshift mutation as the cause of a recessive multiple endocrine neoplasia (MEN)-like syndrome (named MENX) in the rat." (PMID 20492666, 2010). "p27Kip1 can be considered a haploinsufficient tumor suppressor since monoallelic CDKN1B alteration, although rare, has been associated with a major risk of developing tumors and germinal monoallelic p27Kip1 mutation causes the multiple endocrine neoplasia, type 4 (MEN4)." (PMID 35456025, 2022). "Germline mutations in cyclin-dependent kinase inhibitor 1B (CDKN1B) have also recently been identified to be associated with a Multiple Endocrine Neoplasia (MEN) syndrome which may include PHPT, termed MEN4 (OMIM number 610755)." (PMID 26257968, 2015). "These abnormalities are often linked to syndromes such as Multiple Endocrine Neoplasia (MEN-1, MEN-2A, MEN-4) or mutations in genes such as CASR, CDKN1A, CDKN1B, CDKN2C, and RET." (PMID 41597072, 2025). "Importantly, the phenotype observed in mice is fairly well recapitulated also in humans affected by the syndrome of multiple endocrine neoplasia (MEN) that carry germline CDKN1B mutations." (PMID 30065701, 2018). "MEN syndrome is an umbrella term used to describe a family of tumor syndromes ultimately characterized by histologically similar tumors arising in patients and families with mutations in one of four genes: MEN1, RET, CDKN1B, and MAX." (PMID 39336996, 2024). "During the analysis of the sample, specific attention was paid during WES to the genes associated with multiple endocrine neoplasia (CDKN1B, RET, MEN1) and TSC genes, but no variants clinically relevant to the described phenotype of the patient were observed." (PMID 34573383, 2021). "Human germline CDKN1B mutations are associated with approximately 2% of the cases of MEN1 mutation-negative multiple endocrine neoplasia." (PMID 28533356, 2017).
multiple endocrine neoplasia (continued). "Multiple endocrine neoplasia (MEN) syndromes are part of a spectrum of clinically well-defined tumor syndromes ultimately characterized by histologically similar tumors arising in patients and families with mutations in one of the following four genes: MEN1, RET, CDKN1B, and MAX." (PMID 39336996, 2024). "The fourth type of multiple endocrine neoplasia (MEN) is known as a rare variant of MEN presenting a MEN1-like phenotype and originating from a germline mutation in CDKN1B." (PMID 35355569, 2022). "Decreased mRNA and protein expression of CDKN1B were confirmed in the proband's peripheral blood, which is not seen in MEN syndrome patients." (PMID 23505216, 2013). "Since the occurrence of multiple endocrine neoplasia later in life in sporadic cohorts with clinical MEN-1 show that most are genetically negative for mutations in MEN1 and CDKN1B, the cause of the coexistence of acromegaly and PHP remains unclear." (PMID 32311048, 2020).
lymphoma (18 papers, 1999 to 2022). A malignant (clonal) proliferation of B- lymphocytes or T- lymphocytes which involves the lymph nodes, bone marrow and/or extranodal sites. "CDKN1A/p21 and CDKN1B/p27 have also been reported to be EZH2 target genes in lymphoma cell line SUDHL4, and suppressed by H3K27-trimethylation." (PMID 27998273, 2016). "Finally, in p21-KO lymphomas, p27Kip1 (CDKN1B) functions in a p21-independent manner to induce cell cycle arrest after SAHA treatment." (PMID 33117804, 2020). "Mice lacking the p27Kip1 Cdk inhibitor (Cdkn1b) exhibit increased susceptibility to lymphomas from the Maloney murine leukemia virus (M-MuLV), and exhibit a high frequency of viral integrations at Xpcl1 (Kis2), a locus on the X-chromosome." (PMID 21412408, 2011).
neuroendocrine tumors (18 papers, 2008 to 2024). "MEN4 (previously termed MENX) was initially discovered in a rat, which developed highly penetrant multiple neuroendocrine tumors within the first year of life, with the causative gene (CDKN1B) discovered a few years later." (PMID 38038882, 2024). "In this report, we describe two patients developing a neuroendocrine tumor and carrying a germline mutation in CDKN1B." (PMID 35355569, 2022). "Mutations in cyclin-dependent kinase inhibitor, CDKN1B (p27) or loss of CDKN1B expression have been observed in gastroenteropancreatic neuroendocrine tumors." (PMID 30250431, 2018). "Whole genome profiling of small intestine neuroendocrine tumors revealed recurrent mutations in the cyclin dependent kinase inhibitor CDKN1B in only 8% of cases." (PMID 28903345, 2017). "CDKN1B is also frequently heterozygously inactivated in small intestine neuroendocrine tumors, in sporadic parathyroid adenomas and germline inactivated in MEN4, a newly defined subtype of MEN, human autosomal dominant disorders characterized by the occurrence of spread endocrine tumors." (PMID 33316141, 2021). "Furthermore, we observe distinct drivers which are enriched in somatic aberrations in pancreatic (MEN1, ATRX, DAXX, DMD and CREBBP) and midgut-derived neuroendocrine tumors (CDKN1B)." (PMID 34326338, 2021). "ACTB, CDKN1B, GAPDH, GRB2, RHOA and SDCBP are potent reference genes in neuroendocrine tumors of the lung." (PMID 27802291, 2016). "In the present study, ACTB, CDKN1B, GAPDH, GRB2, RHOA and SDCBP were identified as suitable reference genes in neuroendocrine tumors of the lung." (PMID 27802291, 2016).
osteosarcoma (18 papers, 2006 to 2024). A usually aggressive malignant bone-forming mesenchymal neoplasm, predominantly affecting adolescents and young adults. "Our own aCGH analysis of 15 osteosarcoma patient samples detected loss of CDKN1B in nine of 15 samples (our unpublished data)." (PMID 21197465, 2011). "Through regulation of CDKN1B, miR-221-3p suppressed proliferation, migration ability, and invasion ability in osteosarcoma cells." (PMID 32943991, 2020). "We also determined the expression of CDKN1B mRNA by RT-qPCR using RNA extracted from the 5 osteosarcoma tumor cell lines and 50 patient osteosarcoma tumors." (PMID 30992462, 2019). "Since these genes are overexpressed in osteosarcoma tumors, our data reveal that high CDKN1B expression and cytoplasmic localization also predict metastatic potential." (PMID 30992462, 2019). "This gene is widely studied in other sarcoma types such as Kaposi’s sarcoma and osteosarcoma, which exhibit aberrant CDKN1B subcellular localization." (PMID 30200635, 2018). "Furthermore, several studies have demonstrated that osteosarcomas’ overexpression of miR-802 impedes the PI3K/AKT pathway by targeting CDKN1B." (PMID 37432583, 2023). "Despite not being published, our own aCGH investigation of 15 osteosarcoma patient samples revealed CDKN1B loss in 9 of the 15 samples." (PMID 37370857, 2023). "Previous studies have shown that miR-221-3p could suppress the expression of cyclin-dependent kinase inhibitor 1B (CDKN1B) directly; Similarly, M2 macrophage-derived miR-221-3p plays an important role in osteosarcoma." (PMID 38952714, 2024). "In human osteosarcoma cells, the induction of SHOX expression elevates CDKN1A and CDKN1B levels." (PMID 34122528, 2021). "Although Antxr1 knockdown was reported to reduce Ccnd1 and to increase Cdkn1a and Cdkn1b expression in osteosarcoma cells, their expression was not changed in the limb cartilage of Antxr1 tg mice compared with that in wild-type mice at E15.5 by microarray analysis (data not shown)." (PMID 32244499, 2020).